YY1 (YY1 transcription factor)
Diseases named in the same sentence as YY1 in open-access papers (continued):
Sharing a sentence is not in itself a finding about the gene and the disease.
lung carcinoma (continued). "Moreover, this binding leads to direct transcriptional repression of RKIP expression which was consistently observed in computational datasets where YY1 was upregulated in lung cancer samples and RKIP was downregulated." (PMID 41327312, 2025). "Transcription factor YY1 might link miR-1260b to kidney disease as it was reported to regulate cell proliferation and apoptosis in lung cancer via miR-1260b." (PMID 38804362, 2024). "Finally, the ability of JPX to inhibit the silencing activity of miR-378a-3p toward its targets GLUT1, NRP1, YY1, and Wnt5a, and thus the contribution to lung cancer, was demonstrated." (PMID 38672608, 2024). "Finally, Co-IP assays showed mutual interactions between RPTOR and YY1 in these lung cancer cell lines." (PMID 38163890, 2024). "The YY1 modulates Lung Cancer Progression and other lung diseases." (PMID 37925496, 2023). "Sencond, XWLC-05, YTMLC-90, and H157 cells were transfected with pGCMV/EGFP-hsa-miR-34a or pGCMV/EGFP-hsa-miR-NC plasmids to demonstrate whether high expression levels of miR-34a correlated with the expression of PTEN, CDK6, and YY1 in lung cancer." (PMID 33796457, 2021). "Furthermore, our findings demonstrated that YY1 functioned as a tumor suppressor gene in initiation and progression of lung cancer in Gejiu and Xuanwei County." (PMID 33796457, 2021). "Some studies have shown that YY1 mainly acts as a tumour suppressor in pancreatic cancer, however, most studies have shown that YY1 exists as a oncogene, such as in gastric cancer and lung cancer." (PMID 33942988, 2021). "However, our present findings showed that miR-34a overexpression led to enhanced YY1 expression at both mRNA and protein level in Xuanwei and Gejiu lung cancer." (PMID 33796457, 2021). "Previous findings confirmed that YY1 could act as both oncogene and tumor suppressor gene in breast cancer and lung cancer." (PMID 33796457, 2021). "However, some research confirmed that YY1 served an oncogene role in the occurrence and development of lung cancer." (PMID 33796457, 2021). "We also noticed that lncRNA PVT1 expression in lung cancer cells could be regulated by a transcription factor YY1." (PMID 34805417, 2021). "Also, YY1-induced ZFPM2-AS1 has been discovered to promote cell growth in lung cancer by upregulating TRAF4." (PMID 34863279, 2021). "For example, previous research showed that YY1 acted as a tumor suppressor gene in lung cancer." (PMID 33796457, 2021). "Therapeutic strategies that target Kras/YY1/ZNF322A/Shh signaling axis may provide new insight on targeted therapy for lung cancer patients." (PMID 32929330, 2020). "Luciferase reporter assays showed that, in comparison to the construct with the rs17079281[C] allele, the construct with the rs17079281[T] allele had significantly reduced luciferase activity in the in 293T cells and lung cancer cells A549 with YY1 overexpression." (PMID 32231272, 2020). "In addition, knockdown of ZNF322A or YY1 attenuated HUVECs migration ability in CM from H460 KrasQ61H lung cancer cells." (PMID 32929330, 2020). "YY1 facilitates lung cancer progression by promoting lncRNA-PVT1 transcription." (PMID 32681092, 2020). "YY1 contributes to lncRNA-PVT1 activation during lung cancer progression." (PMID 32280300, 2020). "Among other factors that might interfere with YY1 function in lung cancer cells, miR-29a and miR-186 have received significant attention." (PMID 31824839, 2019). "YY1 is overregulated in three lung cancer datasets and downregulated in PAH dataset." (PMID 31867044, 2019). "YY1 is upregulated in lung cancer tissues, and is related to tumor size." (PMID 30737371, 2019). "Based on UCSC database (ChIP-Seq) search, we found that YY1 was restricted to the BCCIP transcriptional start site proximal region in different types of cell lines including human lung carcinoma type II epithelium-like A549, human liver hepatocellular carcinoma HepG2 and human colon cancer HCT116." (PMID 27535137, 2016).
lung carcinoma (continued). "Importantly, the reverse expression pattern of YY1 and RKIP that we observed in LUAD and LUSC might suggest an explicit YY1/RKIP cross-talk in lung cancers, with possible clinical significance." (PMID 37894300, 2023). "The four TFs (YY1, ZEB1, NR4A2 and E2F1) found coexpressed and identified with the DAVID-Opossum analysis have evidence of its association with tumorigenic processes, that could relate them to establishment of lung cancer." (PMID 31867044, 2019). "The authors emphasize that while indirect regulatory mechanisms involving NF-κB and Snail have been proposed in other studies, their data provide direct mechanistic evidence that YY1 itself binds to and represses RKIP expression in lung cancer cells." (PMID 41327312, 2025). "Prior research has demonstrated that high AATF expression can lead to the generation of reactive oxygen species (ROS), which amplify YY-1/EGFR/MnSOD signaling and enhance cancer cell invasion in lung cancer." (PMID 39911629, 2025). "Initially, lentiviral CRISPR-Cas9 technology was employed to knockout YY1 in multiple EGFR-mutant, KRAS-altered, or ALK-rearranged lung cancer cell lines using two independent sgRNAs, and cell viability was significantly inhibited without exception." (PMID 39604408, 2024). "We initially investigated pan-cancer the expression of YY1 and PEBP1, and found higher YY1 mRNA levels in HNSC, lung cancer (both LUAD and LUSC), ESCA, BRCA, and BLCA, compared to their corresponding normal tissues." (PMID 37894300, 2023). "This evidence supports our findings and strongly suggests that a high intake of ω-6 PUFAs leads to a more aggressive phenotype of lung cancer mediated through pro-tumor oxylipins and high expression of VEGF-A, CD31, YY1, COX-2 and TGF-β." (PMID 35682855, 2022). "Transcription factor YY1 plays a role in promoting transcription by combining with the promoter region of lncRNA PVT1, increases the proliferation of lung cancer cells, and inhibites their apoptosis." (PMID 33542193, 2021). "We performed IHC analysis to examine the expression of YY1, ZNF322A, Shh and CD31 in surgically resected tumor specimens from 133 lung cancer patients." (PMID 32929330, 2020). "Here we show that YY1 transcription factor is a crucial mediator between Kras and ZNF322A in enhancing lung cancer progression." (PMID 32929330, 2020). "Clinical data confirm the important connection between MCT-1 activity and YY1, EGFR and MnSOD, as well as the development of malignant microenvironments in lung carcinoma." (PMID 28394354, 2017). "In this study, computational analysis revealed that YY1 negatively regulates RKIP expression in lung cancer, as corroborated by the deposited YY1-ChIP-Seq experiments and validated by their robust negative correlation." (PMID 37894300, 2023). "Accordingly, the results of our analysis show that YY1 is considerably upregulated in HNSC, breast, bladder, and lung cancers (LUSC and LUAD), while PEBP1 is significantly downregulated in all kidney and lung cancer subtypes, as well as in LIHC, HNSC, and STAD." (PMID 37894300, 2023). "In this study, we also report significant differences between high and low YY1 expression in different subtypes of BRCA, KIRC, LUAD, LUSC, and STAD, as well as between high and low PEBP1 expression in different subtypes of KIRC and lung cancers." (PMID 37894300, 2023). "Besides, the activation of MCT-1 oncogene capably induces YY1-EGFR signaling axis that promotes MnSOD expression, mitochondrial ROS generation, lung cancer cell invasion and tumor progression." (PMID 32059469, 2020).
lung carcinoma (continued). "Our findings not only present a previously undefined regulatory mechanism by which ZNF322A synergizes KrasG12D-induced lung tumorigenesis but also indicate that dysregulation of YY1/ZNF322A transcriptional axis promotes expression of angiogenic factor Shh and cancer progression in lung cancer." (PMID 32929330, 2020). "However, the long form of spleen tyrosine kinase (SYK-L), was shown to directly interact with YY1 and interfere with the expression of SLUG and thereby the SYK-L functions as a tumor suppressor and reduce the invasiveness of lung cancer cells." (PMID 31824839, 2019). "It was determined that YY1 could bind to UPLA1 at sites 1: 280 to 291, 2: 633 to 644, 3: 636 to 641 and 4: 912 to 923, and reverse regulate the expression of lncRNA-UPLA1. miRNA also participates in YY1-regulated lncRNAs network in lung cancer." (PMID 36626426, 2022). "Therefore, future studies will be required to elucidate the precise mechanisms involved in the downstream molecules of PTEN, YY1 and CDK6 that could contribute to the miR-34a-mediated suppression of lung cancer progression." (PMID 33796457, 2021). "We reasoned that YY1 function might not be restricted to EGFR-mutant lung cancer." (PMID 39604408, 2024). "However, future studies are required on the precise regulatory network involved in the downstream molecules of PTEN, YY1, and CDK6 that could contribute to miR-34a-mediated tumor suppression for the clinical treatment of lung cancer in Gejiu and Xuanwei County, Yunnan Province." (PMID 33796457, 2021).
gastric cancer (44 papers, 2014 to 2025). A primary or metastatic malignant neoplasm involving the stomach. "According to the bioinformatics findings, the expression of ING5, SRF, and YY1 mRNA was higher in gastric cancer than in normal mucosa, and negatively associated with favorable prognosis of gastric cancer patients." (PMID 35747809, 2022). "ING5, SRF, and YY1 were overexpressed in gastric cancer, (P<0.05), and associated with worse prognosis of gastric cancer patients (P<0.05)." (PMID 35747809, 2022). "In addition, miR-584-3p and YY1 were independent prognostic factors associated with favorable and unfavorable outcome of gastric cancer patients, respectively." (PMID 28827574, 2017). "However, the roles and underlying mechanisms of YY1 in the tumorigenesis and aggressiveness of gastric cancer still remain largely unknown." (PMID 28827574, 2017). "Overexpression of YY1 is frequently observed in various human cancers, including breast, bladder, cervical, colon, esophageal, liver, brain, and gastric cancers." (PMID 40688406, 2025). "This study aims to analyze the role of YY1 in gastric cancer, investigate its effect on the tumor microenvironment, and assess its potential as a prognostic marker." (PMID 40088083, 2025). "Emerging evidence has shown that YY1 plays a critical role in the progression of gastric cancer as one study revealed YY1 expression was upregulated in gastric cancer cell lines and primary gastric cancers." (PMID 41327312, 2025). "Upon siRNA-mediated knockdown of YY1 in multiple gastric cancer cell lines there was a marked inhibition of proliferation, monolayer colony formation, G1 cell cycle arrest, and increased apoptosis." (PMID 41327312, 2025). "Similar results were seen in a separate study that demonstrated YY1 facilitates the advancement of gastric cancer using the CCDC43/ADRM1 signaling axis." (PMID 41327312, 2025). "Higher YY1 expression correlated with diminished postoperative progression-free survival (PFS) and disease-specific survival (DSS) rates in TCGA analysis, identifying YY1 as an independent DSS indicator in gastric cancer (GC) patients." (PMID 38347631, 2024). "For instance, a study using gastric cancer cells showed that YY1 directly targets the MMP-14 promoter and enhances its transcriptional activity." (PMID 37444616, 2023). "YY1 is upregulated in various human cancers, including breast, bladder, cervical, colon, esophageal, liver, brain, and gastric cancers, and there is increasing evidence suggesting that it has pro-tumor consequences." (PMID 37444616, 2023). "The promoter domain of PCIF1 is attached directly by YY1, increasing transcription and advancing gastric cancer." (PMID 37779183, 2023). "CREB is strongly associated with inflammation and progression genes, and YY1, which is upregulated in the AGS cell line, is associated with gastric cancer progression." (PMID 37762277, 2023). "According to studies, the circ-ATAD1/miR-140-3p/YY1/PCIF1 axis is essential for the growth of gastric cancer." (PMID 37779183, 2023). "Univariate and multivariate survival analyses demonstrated that T staging, N staging, M staging, pathological staging, and YY1 mRNA expression were closely linked to unfavorable OS and DSS survival of gastric cancer patients (P<0.05)." (PMID 35747809, 2022). "In gastric cancer cells, YY1 knockdown inhibited Wnt/β-catenin, JNK/MAPK, ERK/MAPK, ER, and HIF-1α signaling pathways." (PMID 35747809, 2022). "In TCGA data, there was a positive correlation between ING5 and YY1 mRNA expression in gastric cancer (P<0.05)." (PMID 35747809, 2022). "It has been reported that circ-ATAD1 is overexpressed in gastric cancer and sponges miR-140-3p to upregulate YY1, thereby increasing cancer cell proliferation." (PMID 35505304, 2022).
gastric cancer (continued). "qRT-PCR was applied to identify miR-378c and YY1 in tissues and serum of patients suffering from gastric cancer." (PMID 33794762, 2021). "Immunohistochemistry on samples from gastric cancer patients showed that YY1 expression correlated positively with lymph node metastasis, distant metastasis, and advanced tumor-node-metastasis." (PMID 32226547, 2020). "The link between YY1 and metastasis has been further confirmed by clinical samples from melanoma and gastric cancer patients." (PMID 32226547, 2020). "In 80 fresh gastric cancer specimens, higher protein and transcript levels of YY1 or MMP-14 were observed than those in normal gastric mucosa." (PMID 28827574, 2017). "The tube formation of endothelial cells was increased by treatment with the medium preconditioned by gastric cancer cells stably transfected with YY1." (PMID 28827574, 2017). "In clinical gastric cancer tissues, the expression of YY1 and miR-584-3p was positively or negatively correlated with MMP-14 levels." (PMID 28827574, 2017). "Meanwhile, ectopic expression or knockdown of MMP-14 rescued the gastric cancer cells from alteration in the viability, invasion, and angiogenesis induced by over-expression of miR-584-3p or YY1, respectively." (PMID 28827574, 2017). "We demonstrate, for the first time, that YY1 facilitates the expression of MMP-14 via directly binding to its promoter in gastric cancer." (PMID 28827574, 2017). "We demonstrated that YY1 directly targeted the MMP-14 promoter to facilitate its expression in gastric cancer cells." (PMID 28827574, 2017). "Collectively, these data suggested that miR-584-3p interacted with AGO2 to repress the YY1-facilitated MMP-14 transcription in gastric cancer cells." (PMID 28827574, 2017). "Our evidence indicated that YY1 expression was positively correlated with MMP-14 levels in gastric cancer specimens and cell lines." (PMID 28827574, 2017). "Stable over-expression of miR-584-3p resulted in increased binding of AGO2 and epigenetic markers EZH2, EHMT2, H3K27me3 and H3K9me2, and decreased binding of YY1 to MMP-14 promoter in gastric cancer cells, which was attenuated by knockdown of AGO2." (PMID 28827574, 2017). "In matrigel invasion assay, stable over-expression of YY1 increased the invasion capacity of gastric cancer cells." (PMID 28827574, 2017). "Our findings reveal the novel mechanisms of MMP-14 gene expression associated with gastric cancer progression, and suggest that YY1 and miR-584-3p are potential targets for the therapeutics of gastric cancer." (PMID 28827574, 2017). "miR-584-3p inhibited the in vitro and in vivo tumorigenesis and aggressiveness of gastric cancer cells through repressing YY1-facilitated MMP-14 expression." (PMID 28827574, 2017). "Our results showed that, following the transfection of YY1 siRNA into the HGC-27 gastric cancer cells, ATP6V1A mRNA and protein levels were significantly decreased." (PMID 28592880, 2017). "Higher YY1 expression was observed in gastric cancer cases with deeper gastric wall invasion (P < 0.001), lymph node metastasis (P < 0.001), distant metastasis (P = 0.005), or advanced tumor-node-metastasis (TNM) stage (P < 0.001)." (PMID 28827574, 2017). "Stable over-expression of YY1 resulted in enrichment of YY1 on the MMP-14 promoter in gastric cancer cells." (PMID 28827574, 2017). "Since above evidence indicated that miR-584-3p repressed the binding of YY1 to MMP-14 promoter, we further investigated the effects of miR-584-3p over-expression on YY1-facilitated MMP-14 levels in cultured gastric cancer cells." (PMID 28827574, 2017). "Our findings additionally suggest that the RKIP–NICD signaling axis is not only critical for controlling cancer progression and metastasis, at least in lung, cervical, and gastric cancers, but also for regulating the NF-kB/Snail/YY1/RKIP loop." (PMID 26716415, 2016).